CXCL10 (C-X-C motif chemokine ligand 10)
Diseases named in the same sentence as CXCL10 in open-access papers (continued):
Sharing a sentence is not in itself a finding about the gene and the disease.
systemic lupus erythematosus (continued). "In addition, multiple chemokines, including CCL2, CCL5, and CXCL10, were expressed at higher levels in PVAT and plasma from lupus mice." (PMID 37006244, 2023). "Thus, renal CXCL9 and CXCL10 are decreased at the transcript and protein levels in lupus prone MRL/lpr Fli-1+/−- mice and suggests FLI-1 modulates CXCL10, CXCL9 expression in the kidneys during lupus nephritis." (PMID 37790939, 2023). "Since reducing FLI-1 decreases expression of CXCL10, FLI-1 may be an alternative drug target for lupus, an ongoing focus in our lab." (PMID 37790939, 2023). "Levels of chemokines CCL2, CXCL10 and CCL19 in lupus patients’ serum were measured by ELISA." (PMID 35207538, 2022). "By RNA-Seq, we found that gene expression of local chemokines in the kidney of lupus-prone mice was altered, and qRT-PCR further confirmed down-regulated expression of CXCL1, CCL2, and CXCL10 in the kidney of IL-22 or IL-22R KO MRL/lpr mice compared with MRL/lpr mice." (PMID 33717066, 2021). "STAT1 may be an important driver of lupus pathogenesis with STAT1 serving as an expression enhancer of CCL2 and CXCL10 in patients with high levels of STAT1." (PMID 24451065, 2014). "In the present report, RhoA mRNA expression further is shown to be higher in the PBMCs of lupus patients when compared to healthy controls, and expression levels correlate positively with type I IFN scores and interferon-induced genes, including CXCL10, OAS1, IFIT3, and MX1." (PMID 38243295, 2024). "In our project,RhoA mRNA expression further has been shown to be higher in the PBMCs of lupus patients when compared to healthy controls, and expression levels correlate positively with type I IFN scores and interferon-induced genes, including CXCL10, OAS1, IFIT3 and MX1." (PMID 37790522, 2023). "CXCL10 is induced by type I and II IFNs as well as TNF, and has been evaluated as a surrogate biomarker to reflect the IFN signature upregulated in autoimmune rheumatic diseases including RA and systemic lupus erythematosus (SLE)." (PMID 27102921, 2016).
hepatocellular carcinoma (59 papers, 2012 to 2025). A malignant tumor that arises from hepatocytes. "Among the six hub DEmRNAs, EZH2 has been demonstrated to be highly expressed in HCC, and injection of EZH2 inhibitor GSK126 induces CXCL10 production from macrophages and causes plasma cell polarization, inhibition of the antitumor T cell response, and hepatoma growth." (PMID 33101367, 2020). "For instance, CXCL10 is known to compete with cell surface heparan sulfate to inhibit dengue virus binding to the Hepa1–6 mouse hepatoma cell line 21, and the virus load is significantly higher in the brain of Cxcl10−/− mice." (PMID 39803542, 2024). "Comparison of the characteristics of patients with Barcelona Clinic Liver Cancer stage C hepatocellular carcinoma stratified by serum CXCL10 levels at the start of the second course." (PMID 38133557, 2023). "Recently, it was reported that CXCL10 contributes to hepatocellular apoptosis through TLR4 on MDSCs instead of its common receptor—CXC motif receptor 3—in patients with hepatocellular carcinoma (HCC), thus leading to cancer recurrence." (PMID 36911674, 2023). "Chemokine pathways involving CXCL10 in the context of the tumor microenvironment of hepatocellular carcinoma have been found to recruit immune cells with anti-tumor activity." (PMID 33574564, 2021). "The response to regorafenib revealed eight genes unique to Huh7 cells and nine unique to HepG2 cells; only CXCL10 was upregulated in both human hepatoma cell lines." (PMID 32397371, 2020). "Increased CXCL10 mRNA expression has been reported in hepatocellular carcinoma and was correlated with the number of infiltrated lymphocytes." (PMID 25605488, 2015). "High CXCL9 and CXCL10 levels inhibit cytolytic CD8+ T cell expression of CXCR3 in hepatocellular carcinomas, and this, in turn, limits lymphocyte recruitment and tumor defense." (PMID 26462153, 2015). "It is reported earlier that recombinant CXCL10 is able to inhibit the binding of DENV to heparan sulfate on hepatoma cell surface." (PMID 23050007, 2012). "CXCL10 was significantly upregulated in hepatocellular carcinoma and melanoma brain metastasis." (PMID 36290882, 2022). "In addition, DENV infection of mouse hepatoma cell line, Hepa1–6, induced the expressions of CXCL10 and CCL5 mRNA." (PMID 23050007, 2012). "Furthermore, In hepatocellular carcinoma, CXCL10/TLR4-mediated MMP14 activation promotes recruitment of monocytic myeloid-derived suppressor cells (MDSCs) after acute liver injury, fueling post-transplant HCC relapse, as evidenced by clinical data, animal studies, and cell-culture assays." (PMID 41404065, 2025). "Relationships of serum C‐C motif chemokine ligand 5 (CCL5) and C‐X‐C motif chemokine ligand 10 (CXCL10) levels with hot immune features have been reported in patients with hepatocellular carcinoma (HCC)." (PMID 38133557, 2023). "The upregulation of LTB and its downstream targets, CXCL10 and NF-κB, was associated with tumorigenesis in HCV-related hepatocellular carcinoma (HCC)." (PMID 33397394, 2021). "Importantly, CCL2, CCL5, and CXCL10 have been described in the process of conversion of senescent premalignant cells mediated by oncogenes activation that could culminate with hepatocellular carcinoma." (PMID 32784775, 2020). "CXCL10 is an IFN-γ induced protein and alterations in its expression have been associated with inflammatory milieu and infectious diseases, whereas CCL5 has been reportedly associated with a crucial role in hepatocellular carcinoma development in murine and human models." (PMID 32784775, 2020). "This augmentation is attributed to the mobilization of CD8+ T cells into the tumor, facilitated by the CXCL10/CXCR3 axis, mainly observed in hepatocellular carcinoma (HCC)." (PMID 39881333, 2025). "IRF1 was found to regulate C-X-C motif chemokine 10 (CXCL10)/chemokine receptor 3 (CXCR3) signaling axis, thereby further activating antitumor immunity in hepatocellular carcinoma (HCC)." (PMID 35664436, 2022).
hepatocellular carcinoma (continued). "We newly found that proinflammatory IL-17+ cells in the peritumoral stroma stimulated hepatoma cells to produce CXCL9, CXCL10 and CXCL11, which in turn led to CXCR3+ B-cell recruitment, maturation and IgG production." (PMID 27853178, 2016). "In this study we clarify that GP73 is down-regulated in hepatoma cells at the early stage of HCV infection, and CXCL10 plays an important role in this process." (PMID 24351813, 2013). "Likewise, increased levels of CXCL10, CXCL12, and CXCL14 in hepatocellular carcinoma patients correlated with favorable survival rates." (PMID 38275602, 2024). "To test whether CXCL10 might directly influence tumor cell proliferation as tumor cells can express CXCR3, we performed a proliferation assay with the human hepatoma cell line HUH7." (PMID 35897689, 2022). "Thus, we alternatively stimulated HepG2 cells (human hepatoma cell line) with Pg-derived LPS or human recombinant IL-1β as positive control and examined mRNA expressions of CCL2, CXCL10, and FOXO1 using real time PCR." (PMID 34526589, 2021). "The TLR3/IFN-β/MDA5/CXCL10 axis demonstrated by our study corroborates previous findings of the role of MDA5 in regulating CXCL10 expression in glomerular mesangial cells, brain microvascular endothelial cells, and hepatocellular carcinoma cells." (PMID 33387195, 2021). "IL-25 has been found to activate M2 TAMs, induce the expression of chemokine CXCL10, and promote epithelial-mesenchymal transition (EMT) in hepatocellular carcinoma (HCC), thereby facilitating tumor progression and metastasis." (PMID 38835386, 2024). "Sitagliptin increases CXCL10 expression by inhibiting dipeptidyl peptidase IV (DPPIV) and regulates lymphocyte transport to hepatocellular carcinoma (HCC) to promote regression (NCT02650427)." (PMID 35269786, 2022). "We have previously reported the role of the transcriptional factor NF-E2-related factor 2 (Nrf2) in cancer-TAM interactions in hepatocellular carcinoma (HCC) and pancreatic cancer and cancer-CAF interactions through IL-6 and CXCL10 in pancreatic cancer." (PMID 33659044, 2021).
acute respiratory distress syndrome (56 papers, 2015 to 2025). Progressive and life-threatening pulmonary distress in the absence of an underlying pulmonary condition, usually following major trauma or surgery. "In COVID-19-associated cytokine storms, heightened expression of CXCL10, CXCL8, and CCL2 has been implicated in the pathogenesis of acute respiratory distress syndrome (ARDS)." (PMID 41268545, 2025). "It was also shown that DDX58 and CXCL10 genes were induced after infection and significantly enriched in acute respiratory distress syndrome." (PMID 36614310, 2023). "The gene CXCL10 was identified as a potential biomarker for the diagnosis and treatment of acute respiratory distress syndrome." (PMID 35140545, 2022). "As the disease enters these phases, upregulation of pro-inflammatory mediators like CXCL10 become predictive of the clinical course and approximately 20% of these patients go on to develop acute respiratory distress syndrome (ARDS)." (PMID 35261923, 2022). "Previous studies have demonstrated that highly elevated IL-6, IL-1, TNF-α, IFN-γ, MIP, CXCL10 are major causes of ARDS (acute respiratory distress syndrome) and mortality, and TGF-β1 could restrict inflammatory response." (PMID 25909459, 2015). "For example, CXCR3, the receptor for CXCL10 and CXCL11, is commonly associated with expression on T cells and lymphocytes but has been shown to be expressed on lung neutrophils from patients with acute respiratory distress syndrome." (PMID 37809107, 2023). "Research has proved that the increased level of CXCL10 in the lung with acute respiratory distress syndrome was largely attributed to infiltrated neutrophils, and that neutralization of CXCL10 could ameliorate lung injury induced by lipopolysaccharide." (PMID 36304166, 2022). "Moreover, SARS-CoV-2 infection induces an abnormal systemic inflammatory response (cytokine storm) that may lead to acute respiratory distress syndrome by producing IL-6, C-X-C motif chemokine 10 (CXCL10), and INF-1." (PMID 38260010, 2023). "CXC chemokine ligand 10 (CXCL-10), a chemokine important for Th1 polarization and potentially involved in the development of acute respiratory distress syndrome (ARDS), has been shown to be elevated both in SARS patients and ferrets infected with SARS-CoV." (PMID 33468694, 2021). "Both CXCL10 and its cognate receptor CXCR3 are expressed by activated neutrophils and are responsible for their recruitment to the lungs in acute respiratory distress syndrome models." (PMID 28852269, 2017). "In acute respiratory distress syndrome, CCL2 and CXCL10 affect the recruitment of neutrophils." (PMID 37958973, 2023). "Whereas most infections are asymptomatic or mildly symptomatic, SARS-CoV-2 can trigger an explosive inflammatory response (cytokine storm) primarily mediated by IL-6, C-X-C motif chemokine 10 (CXCL10), and type 1 interferon, leading to acute respiratory distress syndrome." (PMID 35359954, 2022). "In this vein, during acute respiratory distress syndrome (ARDS), recruited alveolar neutrophils and Mos/macrophages acquire a classically activated phenotype (Mo1/M1) responsible for the release of several growth factors and proinflammatory cytokines, including CXCL1, CXCL2, CXCL10, CCL2, and TNF-α." (PMID 39940787, 2025). "CXCL10 levels were increased in SARS-CoV-2 infected patients, especially those with acute respiratory distress syndrome (ARDS)." (PMID 36366543, 2022). "The resulting acute respiratory distress syndrome (ARDS) and extrapulmonary multi-organ dysfunction are provoked by the excessive production of pro-inflammatory cytokines (IL-6, CXCL8) and chemokines (CXCL10, CCL5, CCL2), a phenomenon also referred as cytokine storm." (PMID 35013790, 2022). "The role of C-X-C motif chemokine 10 (CXCL10), a pro-inflammatory factor, in the development of acute respiratory distress syndrome (ARDS) remains unclear." (PMID 28046003, 2017).
colitis (56 papers, 2008 to 2025). Inflammation of the colon. "Treatment with anti-CXCL10 antibodies attenuated colitis in IL10-deficient mice and in DSS colitis and reduced cell infiltration to the lamina propria." (PMID 34017333, 2021). "CXCR3+ T cells are activated and recruited into inflammatory sites by CXCL10 and have been previously associated with colitis in mice." (PMID 20360984, 2010). "To determine whether CCL5 and CXCL10 are required for DSS-induced colitis, we obtained WT, Ccl5- and Cxcl10-deficient mice from the Jackson Laboratory and treated them with 5% DSS." (PMID 40749055, 2025). "To substantiate these findings, we further showed that mice deficient in CCL5 or CXCL10 could ameliorate the in vivo pathogenesis of colitis and CRC." (PMID 40749055, 2025). "Mouse models of colitis provide further support for a pathogenic role of CXCL10 in UC." (PMID 20360984, 2010). "Given the essential role of CCL5 and CXCL10 in TH17-mediated protection in colitis models, their absence in mice is expected to diminish the therapeutic efficacy of TH17 adoptive cell therapy." (PMID 40749055, 2025). "CXCL10 is a pro-inflammatory cytokine with increased expression in the colonic epithelium of mice with colitis." (PMID 40076032, 2025). "Consistently, higher levels of pro‐inflammatory Il1b, Il6, Tnf, Cxcl2 and Cxcl10 mRNA were detected in the colon of Otub2–/– mice, further consolidating the more severe colitis in these mice." (PMID 39358938, 2024). "In another study, colitis was induced in B6 IL-10 mice, and treatment with anti-CXCL10 during colitis development decreased clinical and histologic disease severity." (PMID 37228614, 2023). "The expression of CXCL10 is very low in the colonic epithelium but substantially increases in colitis under the induction of IFN-γ56,57." (PMID 37328529, 2023). "In murine colitis models, inhibition of CXCL10 reduces intestinal inflammation but also had unexpected effects on intestinal epithelial cells." (PMID 37645250, 2023). "Treatment with anti-CXCL10 during colitis in mice decreased clinical and histological disease severity and lowered mononuclear and TH1 cell recruitment, suggesting its promise as a therapeutic target for IBD." (PMID 38091316, 2023). "CCL2, CCL8, and CXCL10 have been described to recruit inflammatory monocytes and macrophages or Th1 cells to promote colitis, respectively." (PMID 35463017, 2022). "ANOVA showed that the gene expression of all the investigated chemokines (except for Cxcl10) was significantly higher in the colitis group (C) than in the control group (H) (p < 0.01)." (PMID 35163326, 2022). "CXCL10 contributes to systemic inflammation, colonic Th1 recruitment, and adaptive immunity in colitis." (PMID 35462887, 2022). "It has been reported that interferon-y-induced CXCL10 regulates crypt cell proliferation during DSS-induced colitis and that the neutralization of CXCL10 protected mice from epithelial ulceration by promoting crypt cell survival." (PMID 29720595, 2018). "In particular, CXCL10 has received considerable attention in recent years and has been shown to be upregulated during colitis, while CD tissues have been shown to express another ligand, CXCL9, as well as CXCR3." (PMID 29707158, 2018). "We have shown that CXCL10 blockade ameliorates spontaneous experimental colitis, which is mediated predominantly by Th1-type αb TCR+ CXCR3+ cells." (PMID 29707158, 2018). "Further, we have also shown that CXCR3 ligands are upregulated during colitis and anti-CXCL10 treatment inhibits colitis symptoms." (PMID 29707158, 2018). "Administering FNDC4 to mice with DSS-induced colitis resulted in downregulation of expression of the proinflammatory chemokines Cxcl9 and Cxcl10 (Ip10), consistent with the in vitro data in macrophages." (PMID 27066907, 2016). "In DSS colitis CD69−/− CD4 T cell accumulation in colonic lamina propria (cLP) was associated with increased expression of CCL-1, CXCL-10 and CCL-19 genes." (PMID 23776480, 2013).
colitis (continued). "A similar effect of CXCL10 has been noted in potentiating colitis through a massive infiltration of CD4+ T cells, which produce Th1 cytokines." (PMID 24278169, 2013). "Earlier, we have showed that increases in CD4+ T cells in the lamina propria of the colon during colitis are mediated in part by CXCL10." (PMID 24278169, 2013). "These cells also have the capacity to release CXCL10 and are present during Mycobacteria-enhanced colitis." (PMID 18533024, 2008). "Together, the data show that Mycobacteria-dependent host responses, namely CXCL10+ T cells and NK cells, assist in the recruitment and activation of CXCR3+ and CXCL11+ leukocytes to enhance colitis of susceptible hosts." (PMID 18533024, 2008). "IL-10-/- mice develop spontaneous colitis that has similarities to human CD at ~3 months of age under conventional housing conditions which can be abrogated by anti-CXCL10 Ab treatment." (PMID 18533024, 2008). "It has been reported that CXCL10 triggers lymphocyte adhesion to immobilized integrin ligands and enhances colitis through a massive infiltration of CD4+ T cells, which produce Th1 cytokines." (PMID 18957084, 2008). "In addition, the mRNA levels of proinflammatory cytokines including Ccl5, IL-17, IL-6, TNF-α, IFN-γ, CXCL10, and Ccl8 were all found to be increased in colitis tissues of S100A4Smad4-/- mice compared with those in Smad4fl/fl mice." (PMID 39664586, 2024). "Inhibiting CXCL10 reduces the frequency and severity of colitis and intestinal inflammation." (PMID 37328529, 2023). "Blockade of endothelial-induced CXCL10 enhances intestinal crypt cell survival in colitis model." (PMID 36010621, 2022). "Anti-CXCL10 Ab therapy significantly reduced local production of myeloid-derived inflammatory cytokines and intestinal tissue damage in the innate-mediated murine colitis model." (PMID 36248794, 2022). "Importantly, increased Th1 cells within the colon is consistent with recent findings where CXCR3 and its ligands CXCL10/CXCL9 were shown to be enhanced within the colon during immunotherapy-induced colitis." (PMID 36173679, 2022). "Similarly, colitis rats receiving feed with low-molar-mass oat beta-glucan (βGl+) upregulated the expression of only four genes (Ccl19, Cxcl10, Cx3cr1, Cxcr5) in this stage of colitis." (PMID 35163326, 2022). "CXCL10 expression is induced by IFNγ and markedly upregulated in colitis." (PMID 34017333, 2021). "In addition, the abrogation of colitis in IL-10−/− mice with the deletion of CXCL10 further emphasized its role in IBD47." (PMID 29720595, 2018). "However, systemically, CXCL10 levels were increased with QBECO treatment in both experimental colitis and in UC patients." (PMID 30319652, 2018). "Pioglitazone significantly reduced CXCL10 levels in two models of colitis (dextran sodium sulfate and 2,4,6-dinitrobenzene sulfonic acid-mediated colitis) and dose-dependently reduced CXCL10 levels from activated HT-29 colon epithelial cells and THP-1-derived macrophages." (PMID 25722716, 2015). "In DSS colitis model this was at least partially dependent on the increased expression levels of the chemokines CCL-1, CXCL-10 and CCL-19 in the colon of CD69-deficient animals, as neutralization of these three chemokines significantly improved the histopathological picture in colon." (PMID 23776480, 2013). "The numbers of MLN and LP DCs subsets expressing CXCL9 and CXCL11 after the onset of colitis were significantly increased during live Mycobacteria-enhanced colitis than in the other groups with the exception of MLN CXCL10+ myeloid DCs that were elevated following live bacterial challenge." (PMID 18533024, 2008). "The siRNA-mediated knockdown of Otud5 resulted in the development of severe DSS-induced colitis even with MDP activation of NOD2 through the upregulation of colonic expression of IFN-α and CXCL10." (PMID 41155222, 2025).